INS (insulin)
Diseases named in the same sentence as INS in open-access papers (continued):
Sharing a sentence is not in itself a finding about the gene and the disease.
endothelial dysfunction (continued). "Adipose tissue releases interleukins and pro-inflammatory cytokines that influence endocrine physiology by accelerating inflammation and endothelial dysfunction, and reducing insulin clearance in the liver (“the portal theory”)." (PMID 32967205, 2020). "ER stress response is now recognized as a converging molecular link which connects insulin resistance, lipid metabolism disturbances, cell death, and oxidative stress to endothelial dysfunction." (PMID 30987118, 2019). "Gal-geun-dang-gwi-tang attenuates endothelial dysfunction by promoting nitric oxide (NO)-cyclic guanosine monophosphate (cGMP) signaling and improves insulin sensitivity in individuals with diabetic atherosclerosis." (PMID 31258478, 2019). "Most importantly, we found that LECS completely restored the endothelial dysfunction in ob/ob mice, probably due to enhanced insulin sensitivity." (PMID 31636807, 2019). "Citrus flavonoids scavenge free radicals, improve glucose tolerance and insulin sensitivity, modulate lipid metabolism and adipocyte differentiation, suppress inflammation and apoptosis, and improve endothelial dysfunction." (PMID 30962863, 2019). "Proposed mechanisms for these effects include oxidative stress; endothelial dysfunction; overactivity of the sympathetic nervous system; changes in immune response in visceral adipose tissues; and altered insulin sensitivity and glucose metabolism." (PMID 30755210, 2019). "Fasting blood glucose, body weight, food intake, glucose and insulin tolerance, oxidative stress, and liver damage as well as vascular complications with respect to endothelial dysfunction were examined." (PMID 31636807, 2019). "Previously, it was found that dermcidin impaired the insulin activity through NO inhibition and the found result of elevated HbA1c level and lower level of NO are the indication of endothelial dysfunction which actually precipitates cardiovascular disease." (PMID 31300527, 2019). "Cilostazol also decreases serum triglyceride and LDL-cholesterol levels, increases HDL-cholesterol levels, improves insulin sensitivity, increases nitric oxide production, prevents production of adhesion molecules, and attenuates endothelial dysfunction." (PMID 30700294, 2019). "l-Arginine is the substrate for production of NO and its second messenger cGMP, so it is expected that part of beneficial effects of l-arginine on insulin sensitivity is related to an amelioration of endothelial dysfunction." (PMID 29052766, 2018). "Although the precise mechanism linking vascular atherosclerosis and NAFLD is ulclear, the following factors have been proposed as possible mechanisms: insulin resistance, inflammation, oxidative stress, and endothelial dysfunction." (PMID 29565984, 2018). "POI patients present several risk factors for the development of cardiovascular diseases (CVD): endothelial dysfunction, abnormal lipid profile, insulin resistance, and insulin action disturbances." (PMID 30347864, 2018). "In our recent study, we indeed found that the intervention of argirein was useful to normalize insulin-mediated endothelial dysfunction via recovering insulin sensitivity." (PMID 30135489, 2018). "Fasted circulating biomarkers of endothelial dysfunction, lipids and insulin sensitivity were assessed the morning after each activity regimen." (PMID 29872225, 2018). "This triad, along with endothelial dysfunction, which can also be induced by aberrant insulin signaling, contribute to atherosclerotic plaque formation." (PMID 30170598, 2018). "Reduced systemic insulin signaling promotes endothelial dysfunction and diminished endogenous vascular repair." (PMID 29796592, 2018). "POI patients often present several risk factors for the development of cardiovascular disease: Autonomic and endothelial dysfunction, abnormal lipid profile, and insulin dysfunction." (PMID 30347864, 2018).
endothelial dysfunction (continued). "Regimens using rapid-acting insulin analogues are effective both in reducing arterial oxidative stress and in improving endothelial dysfunction." (PMID 29460257, 2018). "More recently, several studies reported the high gamma-GT, ALT and FLI values have been associated with elevated levels of total and LDL cholesterol, triglycerides, insulin levels, early carotid plaques and endothelial dysfunction." (PMID 29049384, 2017). "In conclusion, our study using ob/ob mice has shown that inhibition of hepatic GRK2 expression is sufficient to improve glucose homeostasis and insulin sensitivity, which eventually improves endothelial dysfunction in T2DM." (PMID 28814745, 2017). "We have previously shown that chemical inhibition of G-protein-coupled receptor kinase 2 (GRK2) slightly enhances insulin sensitivity and reduces endothelial dysfunction in type 2 diabetic mice." (PMID 28814745, 2017). "Our recent data suggested that hepatic-specific deletion of PTP1B, in addition to improving glucose and lipid homoeostasis and increasing insulin sensitivity, was protective against endothelial dysfunction in response to high fat diet (HFD)." (PMID 28899902, 2017). "They participate in the regulation of lipid metabolism, insulin biosynthesis, adipogenesis, endothelial dysfunction, neoangiogenesis, plaque development and rupture, as well as glucose homeostasis, among others." (PMID 28969085, 2017). "Insulin sensitizations that target pathway-selective impairment in insulin signaling are known to improve endothelial dysfunction." (PMID 28301565, 2017). "Our results show that rapid improvement of glucose concentration leads directly to greater insulin-stimulated Akt/eNOS signal activation and higher NO production levels in endothelial cells, and cures the endothelial dysfunction." (PMID 28814745, 2017). "GGDGT attenuates endothelial dysfunction via improvement of the NO-cylic guanosine monophosphate signalling pathway and promotes insulin sensitivity in diabetic atherosclerosis." (PMID 28883907, 2017). "Increased uric acid production is known to lower the level of endothelial nitric oxide (NO), resulting in reduced insulin utilization by skeletal muscles and endothelial dysfunction." (PMID 29321950, 2017). "In this prospective, the β2 adrenergic receptor seem play a role in both endothelial dysfunction and insulin release." (PMID 26911143, 2016). "NO was shown to modulate insulin sensitivity, and a decreased bioavailability of NO contributes to endothelial dysfunction." (PMID 27616738, 2016). "Iron depletion has been demonstrated to be beneficial in coronary artery responses, endothelial dysfunction, insulin secretion, insulin action, and metabolic control in T2DM." (PMID 26788523, 2016). "This suggests that obese/insulin-resistant subjects are characterized by endothelial dysfunction and endothelial resistance to insulin’s effect on enhancement of endothelium-dependent vasodilation." (PMID 27188597, 2016). "Overexpression of SIRT3 improves endothelial insulin sensitivity and attenuates endothelial dysfunction induced by nutrient excess through inhibiting mitochondrial oxidative stress." (PMID 27000941, 2016). "The primary outcome of this study was changes in postprandial glycemic and triglyceridemic control and secondary outcomes were improvement of insulin secretion and endothelial dysfunction." (PMID 27565734, 2016). "In conclusion, these results demonstrate that endothelial dysfunction in response to insulin plays an important role in MI-related IR." (PMID 25907785, 2015). "Given the involvement of inflammatory and oxidative stresses in endothelial dysfunction, suppression of the NF-κB-dependent inflammatory response and production of ROS by Pic may have be responsible for its restoration of the loss of insulin-mediated phosphorylation of eNOS and production of NO." (PMID 25815690, 2015).
endothelial dysfunction (continued). "IH applied to HFD mice induced a major increase in insulin and leptin levels and prevented endothelial dysfunction by restoring NO production." (PMID 25993257, 2015). "The present study aimed to investigate this, using PA as one of the predominant mediators to induce endothelial dysfunction in HUVECs, by inducing inflammation and ROS formation and by reducing insulin- mediated NO bioavailability." (PMID 25815690, 2015). "Malfunctioning of insulin mechanism and endothelial dysfunction leads to innate immune activation and released several biological markers into circulation." (PMID 24282409, 2013). "Endothelial dysfunction is usually viewed as an imbalance that occurs in an insulin resistant state, where PI3K signaling is impaired and MAPK signaling is heightened." (PMID 24358323, 2013). "NO metabolites, NO synthase inhibitors, thiols, and N-acetyl-β-glucosaminidase (NAGase) are biomarkers suitable for the detection of endothelial dysfunction and oxidative stress during the early stages of impaired response to insulin." (PMID 23691063, 2013). "SUA reduction of the levels of endothelial nitric oxide (NO), which is a mediator of insulin action and increases blood flow to skeletal muscle, induces endothelial dysfunction and enhances insulin resistance in the liver, muscle, and adipose tissues." (PMID 23785457, 2013). "The resulting increase in insulin-mediated NO should be responsible for actions of tectorigenin in amelioration of endothelial dysfunction." (PMID 23840461, 2013). "Hypertriglyceridemia subjects show slower clearance of glucose, larger insulin increases and more extravagant endothelial dysfunction." (PMID 24325472, 2013). "Because loss of insulin-mediated vessel relaxation is a main characteristic of endothelial dysfunction under insulin resistant state, we studied the effect of tectorigenin on insulin-mediated vasodilation in isolated rat aortic rings." (PMID 23840461, 2013). "Lipids, creatinine, microalbuminuria, blood glucose, HbA1c, blood insulin, high sensitivity C-reactive protein and endothelial dysfunction markers." (PMID 21524299, 2011). "It would be intriguing to study effects of RBX on endothelial insulin sensitivity in the clinic to complement existing data solely focusing on the endothelial dysfunction due to impaired acetylcholine-dependent vasodilation." (PMID 21635764, 2011). "Endothelial dysfunction is a key abnormality found in insulin-resistance states and vascular dysfunction." (PMID 19825145, 2009). "Exercise capacity (VO2max) is strongly correlated with insulin sensitivity and endothelial dysfunction." (PMID 19825145, 2009). "Similarly, TNF-α contributes to endothelial dysfunction, increased vascular stiffness, and impaired insulin signaling." (PMID 41602164, 2026). "IR disrupted insulin signaling at the cellular level in the intima by activating inflammation-related genes, leading to varying degrees of oxidation, chronic inflammation, and endothelial dysfunction." (PMID 40761645, 2025). "Disorders in insulin sensitivity and lipid metabolism result in endothelial dysfunction." (PMID 40510524, 2025). "From a mechanistic perspective, the eGDR, as an alternative marker for IR, not only reflects reduced insulin sensitivity but also captures multidimensional dysregulation, including glucose and lipid metabolism disorders, endothelial dysfunction, chronic inflammation, and oxidative stress." (PMID 41299267, 2025). "Another study revealed that a variant of G972R in human endothelial cells impaired insulin-stimulated NO release through the IRS1/PI3-K/PDK-1/Akt insulin signaling pathway, leading to endothelial dysfunction and resulting in increased genetic susceptibility to cardiovascular disease." (PMID 40747301, 2025). "Moreover, vascular and endothelial dysfunction, impaired insulin sensitivity, increased oxidative stress, and podocyte injury can contribute to DN onset due to vitamin D deficiency." (PMID 40575263, 2025).
endothelial dysfunction (continued). "Furthermore, elevated insulin levels in IR stimulate lipid peroxidation and reactive oxygen species (ROS) production, activating inflammatory pathways and worsening endothelial dysfunction, which fosters CMD onset." (PMID 40740646, 2025). "Furthermore, diminished insulin sensitivity potentially contributes to endothelial dysfunction within capillaries." (PMID 39123295, 2025). "Additionally, NO2-induced endothelial dysfunction decreases NO bioavailability, further compromising insulin-mediated vasodilation and glucose delivery to peripheral tissues." (PMID 41009549, 2025). "The abnormal redox signaling also impacts insulin metabolic signaling, endothelial dysfunction, the development of cardiovascular and renal inflammation and fibrosis, and the promotion of pro-inflammatory and pro-fibrotic pathways, all of which result in harm to the target organs." (PMID 40283443, 2025). "Physical activity may lower blood pressure through mechanisms, such as reduced age-related endothelial dysfunction and increased insulin sensitivity." (PMID 39513057, 2024). "Higher uACR levels portend unfavorable traits, including endothelial dysfunction, inflammation, cardiometabolic and renal risks, 8–10 15–23 whereas higher levels of insulin sensitivity, HDL cholesterol, and adiponectin are beneficial cardiometabolic attributes." (PMID 38233076, 2024). "Accumulated evidence demonstrated that circulating free fatty acids like palmitic acid (PA) can induce endothelial dysfunction through disruption of insulin signaling, promoting oxidative stress and inflammation, impairing mitochondrial integrity, and inducing ER stress." (PMID 39765815, 2024). "Several mechanisms have been postulated for the association of mental stress with cardiovascular mortality, including increased sympathetic activity, which can increase ambulatory blood pressure and heart rate, reduced insulin sensitivity, increased platelet aggregation, and endothelial dysfunction." (PMID 38408898, 2024). "In this process, endothelial dysfunction and impaired endothelium-dependent vasodilation may exacerbate insulin resistance by limiting glucose delivery to key target tissues." (PMID 38329798, 2024). "Periodontitis causes immune impairment and systemic inflammation, which can result in dysregulation of bacterial flora, decreased function of islet cells, insulin resistance, impaired fasting blood glucose, and endothelial dysfunction, thus interfering with normal glucose metabolism." (PMID 37389043, 2023). "However, in the current study, we observed no changes in the expression of ET-1, VCAM1, or ICAM1 in TNFα induced endothelial dysfunction in HUVECs when treated with 10 mU/mL of insulin for 24 h." (PMID 37893034, 2023). "Additionally, L3 aortas exhibited endothelial dysfunction in response to acetylcholine, although insulin-induced relaxation remained unchanged compared to controls." (PMID 37833890, 2023). "Blood flow for the supply of hormones and nutrients to muscles is significantly impaired already in pre-diabetic insulin-resistant states due to endothelial dysfunction, as demonstrated by hampered vasodilatory effects of insulin via nitric oxide (NO)-signalling." (PMID 37256099, 2023). "Basic experiments indicated that the impairment of IR can mediate the injury and functional alterations of smooth muscle cells, mononuclear macrophages, and vascular endothelial cells by interfering with the insulin signaling pathway, which in turn leads to endothelial dysfunction." (PMID 37065738, 2023). "We next set out to further interrogate whether insulin treatment may be reducing endothelial dysfunction directly." (PMID 37893034, 2023). "This supports the hypothesis of their contribution to the mechanism of insulin sensitivity management, hypotensive effect, and the improvement of endothelial dysfunction." (PMID 37215635, 2023).
endothelial dysfunction (continued). "Consistent with the effect on PI3K signaling, spinosin could improve insulin-mediated NO production and alleviate the endothelial dysfunction in IR." (PMID 36033948, 2022). "Loss of endothelial Ceacam1 gene caused endothelial dysfunction and reduced vascular integrity without affecting systemic insulin sensitivity." (PMID 35457157, 2022). "This study aimed to characterize metabolic remodeling with changes in insulin-sensitive organs, which could induce endothelial dysfunction in HFHSD-LE2KO." (PMID 35955653, 2022). "Interestingly, such effects on the insulin profile appear to occur within a similar time frame as inactivity-induced endothelial dysfunction, although very few studies have investigated these outcomes together." (PMID 36237532, 2022). "Inflammation and oxidative stress are suspected to play an important role in endothelial dysfunction due to the angiogenic and insulin-dependent pathways that may influence each other." (PMID 35631313, 2022). "The impaired insulin sensitivity during cachexia, which is similar to that present in aging, may be due to endothelial dysfunction and a lower expression of the Akt and mTOR pathways, which form part of the downstream intracellular signaling of insulin." (PMID 35326490, 2022). "Ultimately, this is not surprising, since we did also not observe supporting differences in the potential underlying pathophysiological mechanisms (24-hour blood pressure, insulin sensitivity, lipid profile, inflammatory markers, plasma biomarkers of endothelial dysfunction, and oxidative stress)." (PMID 35133989, 2022). "The RCTs included in our systematic review were not primarily designed to show an effect on CIMT, but on markers of endothelial dysfunction (flow-mediated dilation), insulin sensitivity (steady-state glucose infusion rate/insulin), or albuminuria (albumin-to-creatinine ratio)." (PMID 36992735, 2022). "For example, cumulative exposure to systemic inflammation may promote impaired insulin sensitivity, endothelial dysfunction, increased aortic stiffness, increased CIMT, and vascular inflammation contributing to CVD in patients with psoriasis." (PMID 34728734, 2021). "First, from the arteriolar microcirculation, endothelial dysfunction may damage insulin function to redirect blood flow in the skeletal muscle and reduce glucose uptake, which was mediated by insulin." (PMID 33776922, 2021). "We calculated EDIH and EDIP scores from baseline food frequency questionnaire data and tested their associations with 40 circulating biomarkers of insulin response/insulin-like growth factor (IGF) system, chronic systemic inflammation, endothelial dysfunction, lipids, and lipid particle size." (PMID 34616762, 2021). "Despite translating stem cell therapy for insulin secretion and metabolic homeostasis, utilization of the regenerative capacity of the stem cells to combat the endothelial dysfunction inherent to the disease would bring a holistic approach to disease management." (PMID 34821725, 2021). "Laboratory studies have begun to elucidate potential mechanisms underlying the relationship between poor sleep and adverse cardiometabolic effects including decreased insulin sensitivity, endothelial dysfunction, increased blood pressure, weight gain, and attenuated fat-loss when dieting." (PMID 34069950, 2021). "Apart from translating stem cell therapy for insulin secretion and metabolic homeostasis, utilization of the regenerative capacity of the stem cells to combat the endothelial dysfunction inherent to the disease would bring a holistic approach to disease management." (PMID 34821725, 2021). "Our analysis of the available experimental data suggests possible positive roles of ROS in induction of pro-survival pathways, downstream of the Gi-protein-coupled receptors, which mimics insulin signaling and prevention or improvement of the endothelial dysfunction." (PMID 34205032, 2021).